DGAT1 (diacylglycerol O-acyltransferase 1)
Description:
Catalyzes the terminal and only committed step in triacylglycerol synthesis by using diacylglycerol and fatty acyl CoA as substrates. Highly expressed in epithelial cells of the small intestine and its activity is essential for the absorption of dietary fats. In liver, plays a role in esterifying exogenous fatty acids to glycerol, and is required to synthesize fat for storage. Also present in female mammary glands, where it produces fat in the milk (By similarity). May be involved in VLDL (very low density lipoprotein) assembly. In contrast to DGAT2 it is not essential for survival (By similarity). Functions as the major acyl-CoA retinol acyltransferase (ARAT) in the skin, where it acts to maintain retinoid homeostasis and prevent retinoid toxicity leading to skin and hair disorders. Exhibits additional acyltransferase activities, includin acyl CoA:monoacylglycerol acyltransferase (MGAT), wax monoester and wax diester synthases (By similarity). Also able to use 1-monoalkylglycerol (1-MAkG) as an acyl acceptor for the synthesis of monoalkyl-monoacylglycerol (MAMAG).
Synonyms: ARAT; DGAT; ARGP1; DIAR7
Tractability: Small molecule: a drug acting on it is in phase 2 or 3 trials; a structure with a bound ligand is known; a high-quality ligand is known; it belongs to a druggable protein family. Antibody: its Gene Ontology location is reachable by antibodies, with high confidence; UniProt predicts a signal peptide or a membrane-spanning region. PROTAC: its protein half-life has been measured; a small molecule that binds it is known.
Target class: Enzyme; Transferase
Chemical probes: AZD-7687, AZD3988 (high quality), CHEMBL3235321, DGAT-1 inhibitor 2, GSK2973980A  (high quality), T863 (high quality)
Gene: Protein-coding gene on chromosome 8 (144,314,584 to 144,326,910, reverse strand). Ensembl gene ENSG00000185000.
Subcellular location: Endoplasmic reticulum membrane
Subcellular location (Human Protein Atlas): Endoplasmic reticulum; Nucleoli; Nucleoli rim
Pathways (Reactome):
Metabolism: Acyl chain remodeling of DAG and TAG; Triglyceride biosynthesis
Immune System: Neutrophil degranulation
Gene Ontology:
Molecular function: diacylglycerol O-acyltransferase activity; identical protein binding; protein binding; retinol O-fatty-acyltransferase activity; acyltransferase activity; 2-acylglycerol O-acyltransferase activity; long-chain-alcohol O-fatty-acyltransferase activity; triacylglycerol lipase activity
Biological process: diacylglycerol metabolic process; lipid transport; monoacylglycerol biosynthetic process; triglyceride biosynthetic process; very-low-density lipoprotein particle assembly; lipid storage; long-chain fatty-acyl-CoA metabolic process; triglyceride metabolic process; fatty acid homeostasis; glycerolipid metabolic process; retinoid metabolic process; retinol metabolic process
Cellular component: membrane; endoplasmic reticulum membrane; plasma membrane; specific granule membrane
Genetic constraint (gnomAD): Loss-of-function variants: 61 observed, 71.56 expected, observed/expected ratio (o/e) 0.85, 90% interval 0.69 to 1.05. The upper end of that interval is the gene's LOEUF score, 1.05, which puts it in group 4 of 6, group 1 being the genes least tolerant of losing a copy. Missense variants: 592 observed, 620.62 expected, observed/expected ratio (o/e) 0.95, 90% interval 0.89 to 1.02. Synonymous variants: 290 observed, 248.02 expected, observed/expected ratio (o/e) 1.17, 90% interval 1.06 to 1.29.
Homologues: Orthologues: chimpanzee DGAT1 (100% identical), macaque DGAT1 (97% identical), pig DGAT1 (87% identical), mouse Dgat1 (86% identical), guinea pig DGAT1 (85% identical), rat Dgat1 (85% identical), dog DGAT1 (81% identical), zebrafish dgat1a (65% identical), Caenorhabditis elegans mboa-2 (44% identical), Drosophila melanogaster mdy (42% identical). Paralogues in human: SOAT1 (25% identical), SOAT2 (25% identical).
Diseases named in the same sentence as DGAT1 in open-access papers:
DGAT1 is named in the same sentence as 122 diseases in open-access papers, as found by Europe PMC text mining. Sharing a sentence is not in itself a finding about the gene and the disease. The quoted sentences say what the papers report.
Obesity (89 papers, 2006 to 2025). Accumulation of substantial excess body fat. "Research findings suggest that U. dioica extract modulates key molecular pathways associated with obesity and breast cancer, leading to the downregulation of critical markers like Dgat1, Lpl, Fas, Mcp1, Brca1, and Brca2 in LPS induced adipocytes." (PMID 40153121, 2025). "Loss of function of DGAT‐1 in mice leads to decreased body weight, increased energy expenditure and resistance to diet induced obesity." (PMID 40386326, 2025). "Among the enzymes crucial for triglyceride accumulation in fat tissue associated with obesity, Dgat1, Fas, and Lpl hold significant importance." (PMID 40153121, 2025). "DGAT1 encodes diacylglycerol o-acyltransferase 1, a multichannel transmembrane protein and key metabolic enzyme possibly associated with obesity and other metabolic diseases." (PMID 38166771, 2024). "Mice with DGAT1 deficiency are lean and resistant to diet-induced obesity, while DGAT2 deficiency results in reduction of the majority of fat in the whole body." (PMID 38500157, 2024). "The deficiency of DGAT1 in organisms promotes intestinal insulin release and alters lipid absorption, thus improving obesity and its adverse effects." (PMID 35845812, 2022). "In contrast, the recovery of Dgat1 expression solely in the small intestine renders these mice susceptible to obesity and NAFLD." (PMID 30766961, 2019). "Dgat1-deficient (Dgat1−/−) mice are lean, resistant to diet-induced obesity and show decreased DGAT activity." (PMID 28706193, 2017). "Mice that express DGAT1 exclusively in the small intestine are, however, susceptible to high-fat diet-induced hepatic steatosis and obesity." (PMID 27344248, 2016). "Diacylglycerol acyltransferase‐1 (DGAT1), a key enzyme in triglyceride (TG) biogenesis, is highly associated with metabolic abnormalities, such as obesity and type 2 diabetes." (PMID 26493024, 2016). "DGAT1-deficient (Dgat1−/−) mice are resistant to high fat diet-induced obesity due in part to an increase in systemic energy expenditure induced by body heat loss." (PMID 26246845, 2015). "Chen and colleagues showed that these DGAT1-deficient mice have decreased levels of skeletal muscle TAG after induction of high-fat-diet-induced obesity, in addition to increased sensitivity to insulin and leptin." (PMID 26942223, 2015). "Gut-specific reconstitution of DGAT1 restored postprandial TG excursion and the susceptibility to diet-induced obesity in Dgat1−/− mice, suggesting gut DGAT1 deficiency is necessary for the TG and body weight phenotypes in DGAT1 knockouts." (PMID 23336002, 2013). "DGAT-1 deficient mice are resistant to diet-induced obesity and have increased sensitivity to insulin and leptin, hence the excitment in discovering DGAT inhibitors." (PMID 22007304, 2012). "Interestingly, in a previous study, a deficiency of FABP or DGAT1 caused protective effects in obesity and insulin resistance." (PMID 33954196, 2021). "Dgat1‐deficient mice are resistant to diet‐induced obesity and liver steatosis." (PMID 30766961, 2019). "In contrast, DGAT1-deficient (Dgat1–/–) mice are viable and resistant to diet-induced obesity." (PMID 27223895, 2016). "Moreover, diacylglycerol acyltransferase 1 (DGAT1)-deficient mice are resistant to diet-induced obesity through a mechanism involving increased energy expenditure." (PMID 26942223, 2015). "The development of obesity in mice overexpressing Dgat1 in adipose tissue indicates the critical role Dgat1 plays in the development of obesity and insulin resistance." (PMID 40153121, 2025). "Given Dgat1’s role in adipogenesis, these findings support its therapeutic potential in obesity management." (PMID 40153121, 2025). "DGAT1 knockout mice were viable, generally lean, more leptin- and insulin-sensitive, and resistant to high-fat diet-induced obesity." (PMID 38500157, 2024).
Obesity (continued). "Some studies also indicate that DGAT1-dependent triglyceride storage in macrophages can protect mice from diet-induced obesity insulin resistance and inflammation." (PMID 38549670, 2024). "Since accumulation of excess TGs can lead to the pathogenesis of multiple metabolic disorders, such as obesity, type II diabetes, and fatty liver disease, DGAT1 and DGAT2 have been considered potential targets for the treatment of metabolic diseases." (PMID 38500157, 2024). "Deletion of the Dgat1 gene (Dgat1−/−) increased energy expenditure in mice, improved leptin and insulin sensitivity, and improved resistance to diet-induced obesity and NAFLD." (PMID 36817150, 2023). "This is in line with previous reports that have generally suggested that DGAT1 levels increase during obesity, and its function is important to prevent excessive accumulation of ectopic lipids but not so much to preserve fat mass." (PMID 37602323, 2023). "In an in vivo study, DGAT1−/− mice were resistant to diet-induced obesity, in part due to disruption of lysosomal function, which in turn induced abnormal CLD accumulation in enterocytes." (PMID 36817150, 2023). "Inhibition of DGAT1 was evaluated as a potential treatment modality for patients with obesity and T2D." (PMID 37008937, 2023). "Although currently such a factor remains to be identified, this model is reminiscent of global DGAT1 knockout mice, which exhibit increased energy expenditure, enhanced glucose metabolism, protection from diet-induced obesity, and increased leptin sensitivity." (PMID 37782317, 2023). "The proven viability of DGAT1 null mice initially led to an increase in research into DGAT1 inhibitors for obesity related diseases, but there have since been DGAT1 inhibitors developed for a variety of medical uses, from type 2 diabetes to tumour suppression." (PMID 36277080, 2022). "As DGAT1 has been mooted as a clinical target for combating obesity, several potent and selective small-molecule inhibitors are already available for repurposing." (PMID 35732120, 2022). "DGAT1 is a protein involved in converting diacylglycerol to fatty acyl CoA and triacylglycerol, and DGAT1 upregulation is found in obesity and metabolic diseases." (PMID 36290577, 2022). "DGAT1 knockout mice have been shown to develop resistance to diet-induced obesity and have improved insulin sensitivity due to reductions in the expression levels of genes involved in lipid uptake and oxidation, thus preventing lipotoxicity." (PMID 35159548, 2022). "DGAT1 inhibitors have been a focus of pharma investment, primarily as a means to treat obesity and metabolic effects of diet induced obesity." (PMID 34603294, 2021). "DGAT-1 deficient mice showed a significant reduction in the postprandial increase of plasma TAG and were resistant to diet-induced obesity due to increased energy expenditure." (PMID 31752563, 2020). "DGAT1 has been extensively investigated as a therapeutic target for obesity and obesity-related metabolic disorders such as insulin resistance." (PMID 31345219, 2019). "DGAT1 knockout mice are phenotypically lean and resistant to diet-induced obesity and fatty liver disease." (PMID 30816200, 2019). "This is primarily because DGAT1 mouse knockout (KO) models are resistant to diet-induced obesity, show decreased levels of tissue triglycerides, and have increased sensitivity to insulin and leptin." (PMID 31345219, 2019). "The top predictors, rs10521308 (FTO), rs2206135 (CTNNBL1), cg13438334 (DGAT1), and cg22390041 (ALDH4A1) are located in genes known to be associated with obesity risk." (PMID 30255820, 2018). "Overexpression of DGAT1 in white adipose tissue of mice exposed to high-fat diet leads to increased accumulation of TAGs in adipose tissue and to obesity, but it also improves insulin sensitivity in comparison with wild-type mice." (PMID 30081476, 2018). "Increased inflammation in a murine model of diet-induced obesity can be reversed by overexpression of DGAT1 in macrophages." (PMID 30018616, 2018).
Obesity (continued). "Dgat1 encodes the gene for the enzyme that catalyzes the last step of triglyceride production, and Dgat1 null mice are protected from the development of diet-induced obesity and IR." (PMID 29564328, 2018). "DGAT1 knockout (DGAT1−/−) mice are viable, resistant to diet-induced obesity and fatty liver disease, exhibit increased energy expenditure, and normal insulin and leptin sensitivity." (PMID 27344248, 2016). "This enzyme was previously identified as a priority drug target, as DGAT1 mutant mice are viable and show numerous beneficial metabolic characteristics such as resistance to diet-induced obesity and increased insulin or leptin sensitivity." (PMID 27428418, 2016). "By contrast, overexpressing DGAT1 in the white adipose tissue of mice leads to increased adiposity and a propensity for diet-induced obesity." (PMID 27223895, 2016). "It should be noted that DGAT1 plays a role in the storage of fatty-acyl CoA’s and is a therapeutic target for treatment of obesity." (PMID 25974161, 2015). "For all these reasons, the use of DGAT1 inhibitors as anti-diabetes and/or anti-obesity agents remains uncertain." (PMID 28943619, 2015). "In humans, in addition to the clinical interest in the DGAT1 enzyme as a target for obesity treatment, studies have found related roles for this enzyme in many human disorders, such diabetes, nonalcoholic steatohepatitis and insulin resistance." (PMID 25719207, 2015). "DGAT1 knockout mice were found to be viable and were protected from high-fat diet induced obesity and insulin resistance." (PMID 28943619, 2015). "DGAT1 null mice are known to be resistant to diet-induced obesity, and more insulin sensitive relative to the wild-type; however, the mice exhibit abnormalities in the skin." (PMID 25405858, 2014). "Our results suggest that the intestine is the key tissue in which DGAT1 plays a role in promoting obesity and insulin resistance." (PMID 25405858, 2014). "Mice with a deletion of the DGAT1 enzyme (DGAT1 -/-) are protected from diet induced obesity and show increased sensitivities to insulin and leptin and increased energy expenditure." (PMID 24558447, 2014). "DGAT1 null mice are resistant to diet-induced obesity, and exhibit higher insulin sensitivity compared to the wild-type." (PMID 25405858, 2014). "Potent DGAT1 inhibitors are currently being developed for the treatment of hyper-triglyceridemia and obesity." (PMID 24558447, 2014). "Of the two DGATs identified to date, DGAT1 garnered much attention as a target for the treatment of obesity since DGAT1 knockout mice showed marked resistance to diet-induced obesity." (PMID 23336002, 2013). "Their results also showed the effect of DGAT1 on muscle insulin sensitivity and that DGAT1 transgenic mice were resistant to HFD (high fat diet) – induced obesity." (PMID 23642106, 2013). "Diacylglycerol acyltransferase-1 (DGAT1) is a potential therapeutic target for treatment of obesity and related metabolic diseases." (PMID 23336002, 2013). "It is reported that the inhibition of DGAT1 is a promising strategy for the treatment of obesity and type 2 diabetes in order to attenuate excessive lipid biosynthesis and deposit." (PMID 24527264, 2012). "Genetic disruption of diacylglycerol acyltransferase 1 (DGAT1), which catalyzes the final reaction of triglyceride synthesis, confers dramatic resistance to high-fat diet induced obesity." (PMID 22073239, 2011). "Mice deficient in DGAT1 are viable, have modest decreases in TAG, and are resistant to diet-induced obesity." (PMID 21777418, 2011). "DGAT1 knock out (-/-) mice are lean, resistant to diet induced obesity and have increased insulin sensitivity, while the DGAT2 (-/-) genotype is lethal." (PMID 22073239, 2011). "Our results are consistent with a previous report in showing that Dgat1-/- mice have a lower body fat content than Dgat1+/+ mice and are resistant to diet-induced obesity." (PMID 17239230, 2007).
Obesity (continued). "The decreased adiposity and resistance to diet-induced obesity in Dgat1-/- mice result from an increase in total energy expenditure." (PMID 16448557, 2006). "Remarkably, transplantation of Dgat1-/- WAT conferred partial obesity resistance, enhanced glucose disposal after a glucose load, and increased activation of the insulin signaling pathway in WT recipient mice." (PMID 16448557, 2006). "However, gastrointestinal side effects were observed and several participants discontinued treatment due to diarrhea making the usefulness of DGAT1 inhibition as a novel treatment for diabetes and obesity questionable." (PMID 37008937, 2023). "Diet-induced obesity was associated with an increase in circulating glycerol levels as well as with an upregulation of AQP7 in BAT, which was strongly associated with the increase in the lipogenic factors Pparg2, Mogat2 and Dgat1." (PMID 36834823, 2023). "When the DGAT1 gene was knocked out, a variety of fat metabolism disorders started to occur, such as increases in obesity resistance and energy consumption in mice and decreased fatty acid synthesis and increased oxidative decomposition of fatty acids in the liver." (PMID 37206332, 2023). "In addition, the inhibition of DGAT1 is known to increase energy expenditure and protect against high-fat diet-induced obesity." (PMID 33922621, 2021). "Likewise, the role of DGAT1 is diverse and its overexpression promotes the development of insulin resistance, obesity and fatty-acid induced inflammation." (PMID 32674072, 2020). "In addition, the inhibition of DGAT1 is known to increase energy expenditure and protect against diet-induced obesity." (PMID 31941008, 2020). "Therefore, selective DGAT-1 inhibitors have been developed to manage metabolic diseases such as obesity and type 2 diabetes." (PMID 31752563, 2020). "DGAT1 has been recognized as an anti-obesity target; however, its role in the tumor microenvironment remains unclear." (PMID 30816200, 2019). "However several DGAT1 inhibitors are being developed for treating obesity and other metabolic diseases, and some of these are in clinical trials." (PMID 28877685, 2017). "Moreover, expressing DGAT1 exclusively in the intestine is sufficient to reverse the protection against obesity and hepatic steatosis, normally seen in Dgat1–/–mice fed a diet high in fat." (PMID 27223895, 2016). "Reduction in postprandial TG concentrations upon DGAT1 inhibition in humans have been consistent with animal studies but their development as a therapeutic target for obesity, diabetes, and hyperlipidemia have been hampered due to unwanted gastro-intestinal side effects." (PMID 27344248, 2016). "By this effort, we could map the activity of one group of small molecules to the inhibition of the lipogenic diacylglycerol acyltransferase 1 (DGAT1) enzyme, which is a known human obesity drug target." (PMID 27428418, 2016). "Given the DGAT1 enzymes represent interesting therapeutic targets in obesity, insulin resistance, and in hepatitis C virus infection, it is important that DGAT1 structure-activity relationships are characterized, especially in the absence of any crystal structure of this enzyme or a close homologue." (PMID 25719207, 2015). "In addition, intestinal only expression of DGAT1 abolished the anti-obesity phenotypes of Dgat1−/− mouse while on a high fat diet." (PMID 26246845, 2015). "Here, a decrease in the DGAT1 activity by the treatment of SCE was observed in the study may attribute to its potential to reduce development of obesity as well hyperglycemia induced dis/hyperlipidemia." (PMID 25184241, 2014). "Moreover, the metabolic phenotypes of DGAT1 null mice such as resistance to hepatic steatosis and diet-induced obesity are reported to be lost when DGAT1 is reintroduced into the intestine." (PMID 25405858, 2014).